LEP (leptin)
Diseases named in the same sentence as LEP in open-access papers (continued):
Sharing a sentence is not in itself a finding about the gene and the disease.
Obesity (continued). "In the present work, we hypothesise that temporal fluctuations in ovarian leptin signalling throughout obesity affect the inflammatory response in the organ, through the modulation of NLRP3 inflammasome activity and macrophage infiltration." (PMID 38580672, 2024). "In obesity, there is an increased expression of proinflammatory cytokines and hormones that are produced within adipose tissue, such as interleukin-6 (IL-6), tumor necrosis factor-alpha (TNFa), leptin, angiotensinogen, resistin, and C-reactive protein." (PMID 38672532, 2024). "Additionally, the positive correlation between BMI and CRP, respectively, and leptin levels suggest a link between obesity and inflammation." (PMID 39768291, 2024). "Leptin and adiponectin, hormones secreted by adipocytes, play pivotal roles in regulating energy balance and have the potential to establish connections between obesity and early puberty onset." (PMID 38535297, 2024). "Similarly, oxidative stress and damage are present in the hypothalamus of obesity models and hypothalamic oxidative stress aggravates obesity-induced insulin and leptin resistance." (PMID 38397850, 2024). "Persistently high serum leptin levels as seen in obesity, may lead to the development of leptin resistance." (PMID 39268361, 2024). "Although individuals with obesity have elevated levels of leptin, they may be at least partially resistant to leptin’s metabolic effects." (PMID 39612121, 2024). "Previous work identified leptin-derived fragments with anti-obesity actions." (PMID 39000459, 2024). "Moreover, it is well known that leptin is positively correlated with body mass index (BMI) and other indicators of obesity." (PMID 39125635, 2024). "This self-reinforcing cycle can stimulate SNS and increase BP and could be a further link between leptin and obesity-related hypertension." (PMID 38186879, 2024). "In contrast to leptin, adiponectin circulating concentrations are reduced in obesity." (PMID 39339770, 2024). "Numerous animal studies and a handful of human studies suggested a beneficial role of these metabolites in the prevention and treatment of obesity and its comorbidities by acting as signaling molecules on energy expenditure, lipid oxidation and leptin secretion." (PMID 38321177, 2024). "Correspondingly, it is ablation of ARC POMC, not NTS POMC neurons, which is required for the development of obesity, increased fat mass and glucose intolerance, with the former neurons being stimulated by leptin, while the latter are stimulated by cholecystokinin (CCK) and inhibited by opioids." (PMID 38019584, 2024). "Therefore, increased leptin levels observed in obesity can influence the immune cell population within adipose tissue, potentially leading to an enhanced immune response and inflammation." (PMID 39335642, 2024). "Third, obesity might lead to diabetes mellitus and depression through reduced adiponectin and increased leptin and resistin, indicating the importance of weight control." (PMID 37927197, 2024). "However, leptin is reported to influence energy metabolism to inhibit the development of obesity in rodent and animal models." (PMID 39199293, 2024). "Therefore, the inhibition of some HDACs, such as HDAC6, can act as a leptin sensitizer and anti-obesity factor and can thus be considered a potent therapeutic tool." (PMID 38892574, 2024). "The correlation between rs17713054 SLC6A20-LZTFL1 and obesity is supported by previous research indicating that LZTFL1 may regulate leptin signaling, and participate in the LepRb signaling pathway in the hypothalamus, which controls energy homeostasis." (PMID 39175753, 2024). "Our findings support the existence of a negative feedback loop between TET2 and leptin in adipocytes and reveal a compensatory mechanism for the body to counteract the metabolic dysfunction caused by obesity." (PMID 38561362, 2024).
Obesity (continued). "Interestingly, while adiponectin levels in the bloodstream decrease as body fat increases, in contrast to the anti-obesity effect of leptin, serum leptin levels are positively correlated with body fat content." (PMID 38674828, 2024). "This may suggest that patients who have already been diagnosed with obesity-related sarcopenia and who, after bariatric surgery, have a more significant decrease in muscle strength, have a greater decrease in leptin levels and, consequently, in satiety levels." (PMID 39599699, 2024). "Additionally, leptin, which is secreted by adipose tissue, plays a major role in obesity-r,elated CVD." (PMID 38672532, 2024). "In obesity, elevated levels of leptin are frequently observed, which is known as leptin resistance." (PMID 39275140, 2024). "To investigate the effects of primary mechanisms of obesity-induced cancer on HCC risk, we initially included a total of 263 SNPs as IVs associated with C-reactive protein levels, 6 SNPs with circulating leptin levels, 14 SNPs with adiponectin, 9 SNPs with severe insulin-resistant type 2 diabetes." (PMID 38977823, 2024). "In obesity, however, impaired leptin sensitivity mutes these leptin-mediated changes." (PMID 38766160, 2024). "The inflammatory environment including obesity-rich leptin in obesity triggers these modifications, likely impairing adipogenesis and/or adipocyte maturation, potentially affecting gene expression patterns and exacerbating the chronic inflammatory state in a positive feedback loop." (PMID 39065712, 2024). "Finally, leptin secretion exhibits sex-specific patterns and, when elevated in conjunction with overweight and obesity, contributes to cardiovascular diseases in both sexes." (PMID 39335491, 2024). "The partial reduction of circulating leptin levels through genetic and antibody-blocking approaches improves leptin resistance, thereby decreasing food intake and increasing energy expenditure in obese mice, providing insights into the treatment of obesity." (PMID 38561362, 2024). "Addressing leptin resistance through weight management, lifestyle changes, and pharmacological interventions can help improve reproductive health and enhance fertility in individuals with obesity." (PMID 39767708, 2024). "In individuals with obesity, adipose tissue releases elevated levels of leptin." (PMID 39201522, 2024). "Consequently, the alteration in leptin‐to‐adiponectin ratio plays a crucial role in linking obesity to cancer progression." (PMID 38405061, 2024). "Firstly, leptin plays a crucial role in regulating appetite and energy metabolism, and its elevation may ultimately lead to overweight or obesity." (PMID 38615017, 2024). "However, the chronic activation of astrocytes induced by HFD-related obesity can increase cytokine expression and reduce leptin signaling sensitivity in hypothalamic neurons." (PMID 39590331, 2024). "Additionally, chronic treatment of obesity with leptin promotes preadipocyte differentiation and secretion of pro-inflammatory cytokine TNF-α." (PMID 39564133, 2024). "Despite the great diversity of results, it is evident that some pesticides might promote obesity by altering lipid and glucose metabolism, modifying genes, or altering hormone levels such as leptin." (PMID 39767584, 2024). "High leptin levels and obesity have been observed in NOA group in this study." (PMID 38356829, 2024). "Notably, sucralose-fed rats had the highest glucose (151.5 mg/dL), insulin (6.44 ng/mL), and leptin (25.54 ng/mL) levels, indicating a pronounced impact on obesity-related parameters." (PMID 39449954, 2024). "Obesity is known to be accompanied by decreased serum adiponectin and increased serum leptin." (PMID 39593945, 2024). "Additionally, in obesity, the release of leptin becomes highly stimulated, leading to a state of leptin resistance, altering the regulation of appetite and energy expenditure." (PMID 39339783, 2024).
Obesity (continued). "Moreover, obesity leads to heightened leptin levels and inflammatory markers such as C-reactive protein (CRP), further exacerbating vascular and myocardial injuries." (PMID 38397015, 2024). "Elevated leptin levels in obesity are associated with increased production of inflammatory cytokines, such as TNF-α and IL-6, which further contribute to chronic low-grade inflammation seen in obesity and metabolic syndrome." (PMID 39700087, 2024). "An altered F/B ratio has been observed in obese animal models with a leptin gene mutation as opposed to their lean siblings who did not express the mutations, suggesting that obesity influences gut microbial diversity." (PMID 39596385, 2024). "Similarly, leptin knockout in obesity-derived adipocytes reduced tumor growth of triple negative breast cancer (BT20) which was associated with reduced expression of angiogenesis-promoting genes (e.g., SERPINE1, SNAI2, IL-6, TWIST1, and PTGS2)." (PMID 39439572, 2024). "Moreover, leptin is known to inhibit insulin secretion and plays a significant role in insulin resistance in obesity and type 2 DM." (PMID 38707092, 2024). "Obesity-related hypertension develops due to the overactivation of the sympathetic nervous system, stimulation of the renin-angiotensin-aldosterone system, alterations in adipose-derived cytokines such as leptin, and insulin resistance." (PMID 38373927, 2024). "Furthermore, there is also evidence to show that chronic IH conditions observed in OSA patients stimulate leptin, an obesity biomarker in white adipose tissue, while leptin can further promote production of proinflammatory cytokines." (PMID 39712898, 2024). "It is believed that systemic adipokines, including leptin, may contribute to endothelial activation and dysfunction in COVID-19 patients with obesity." (PMID 39200926, 2024). "The mechanisms and reasons behind exactly how reducing leptin levels in a hyperleptinemic state, like obesity, alleviate disease burden remain unknown." (PMID 39872508, 2024). "High saturated fat intake was associated with increased IL-6 levels (odds ratio = 2.03, 95% confidence interval [CI] = 1.00–4.11, p < 0.047), whereas high total fat intake elevated leptin levels by 2.14-fold (95% CI = 1.12–4.10, p < 0.021) in participants with obesity." (PMID 39700087, 2024). "However, hyperleptinemia in obesity principally resulted from leptin resistance, which had a pro-inflammatory role." (PMID 38566090, 2024). "In univariate analyses of obesity-linked systemic factors and PLOD2, significant correlations were found for lean mass (r2 ​= ​0.20), fat mass (r2 ​= ​0.20), serum cholesterol (r2 ​= ​0.17), serum triglycerides (r2 ​= ​0.19) and serum leptin (r2 ​= ​0.10)." (PMID 38694906, 2024). "DED was associated with higher leptin and cholesterol concentrations, and having insulin resistance, but not with any measure of obesity or inflammation." (PMID 38463689, 2024). "Furthermore, leptin, a well-known hormonal marker of obesity, is extremely sensitive to variations in energy consumption, especially when there is an energy deficit." (PMID 39290329, 2024). "Therefore, leptin is endowed with a critical role in controlling body weight and preventing obesity." (PMID 39000142, 2024). "In addition to incretin-based therapeutics, the hormone leptin is thought to be a driving force for the treatment of obesity through reducing food intake and increasing energy expenditure." (PMID 38310105, 2024). "In addition to these, we noticed differences in the impairment of glucose homeostasis induced by obesity between LanCL1 Ctr and cKO mice, and the obese cKO mice had higher levels of blood glucose, insulin, and leptin than the obese Ctr mice." (PMID 38397850, 2024). "Low serum leptin contributes to the development of severe obesity." (PMID 39002670, 2024). "Consequently, reducing circulating leptin levels emerges as an effective therapeutic strategy for managing obesity-related consequences." (PMID 39335491, 2024).
Obesity (continued). "Indeed, we observed that early-onset obesity in rats increases NE levels in the ovary when they are adults, which occurs alongside high leptin levels." (PMID 39963180, 2024). "In the study, obesity and LEP hypermethylation were proportional, but they detected low LEP methylation in children with high body mass index scores and speculated that this situation might be related to high birth weight but without a definitive conclusion." (PMID 39594868, 2024). "Furthermore, in people with obesity, hyperlipidemia, elevated levels of circulating leptin, and baroreflex sensitivity dysfunction result in the overactivation of the sympathetic nervous system." (PMID 38892574, 2024). "Second, obesity affects cognitive function by regulating leptin and adiponectin levels." (PMID 39634656, 2024). "Patients with obesity had higher leptin levels than controls." (PMID 38454515, 2024). "Obesity, characterized by excessive accumulation of adipose tissue leading to chronic low-grade inflammation, leptin and insulin resistance, and altered activity of the hypothalamic-pituitary-adrenal (HPA) axis, potentially triggering depressive symptoms directly or indirectly." (PMID 39394060, 2024). "Another mechanism for obesity-induced TD may be account for leptin, which is a hormone predominantly secreted by white adipose tissue and could regulate the HPGA axis by stimulating GnRH release." (PMID 38978622, 2024). "Moreover, elevated leptin levels in obesity inhibit androgen production, exacerbating hypogonadism in affected individuals." (PMID 38892561, 2024). "Leptin levels are positively correlated with body mass index (BMI) and obesity." (PMID 39012360, 2024). "Furthermore, the assessment of leptin levels, which are elevated in obesity, and, respectively, adiponectin levels, which are lowered in the case of insulin resistance, can also contribute to completing this picture." (PMID 39000383, 2024). "Mutations that perturb leptin-melanocortin signaling are known to cause hyperphagia and obesity, but energy expenditure has not been well studied outside rodents." (PMID 38446876, 2024). "An important limitation of monogenic models deficient in leptin is that they do not accurately represent the pathogenesis of obesity in humans." (PMID 38339160, 2024). "Thus, leptin was initially considered as a potential effective treatment for obesity via its satiety effects." (PMID 38256208, 2024). "While OLZ, CLZ, and QTP are known to significantly increase leptin levels, it remains uncertain whether their influence on leptin levels is direct or mediated indirectly through effects on obesity and subsequent leptin resistance." (PMID 38802393, 2024). "As seen with increased circulating insulin in T2DM, excess leptin in the setting of obesity also promotes leptin resistance, but whether altered leptin signaling or other traits of MetS foster ADRD-related pathologies is not well understood." (PMID 38416718, 2024). "Alterations in adiponectin and leptin levels, and their interactions, may significantly influence the development of obesity and diabetes." (PMID 39474247, 2024). "On the one hand, combining leptin and leptin sensitizers may overcome leptin resistance and combat obesity." (PMID 39872218, 2024). "Future studies should broaden their scope to include a wider array of genes, such as MC4R, LEP, and POMC, to provide a more comprehensive understanding of the combined association between these genes and breastfeeding and their association with obesity." (PMID 39389470, 2024). "Leptin resistance makes simple obesity treatment in the form of leptin administration ineffective." (PMID 39057043, 2024). "Among all the bioactive molecules deregulated in obesity is the adipokine leptin." (PMID 38228661, 2024). "However, it has been widely believed that the administration of exogenous leptin, thereby increasing the hormone’s circulating level, should inhibit food intake and function as an obesity treatment strategy." (PMID 38541047, 2024).
Obesity (continued). "Circulating leptin levels are positively related to obesity in lean humans and animals." (PMID 39125635, 2024). "Paternal obesity alone did not influence offspring food intake or leptin levels, while maternal obesity was linked to hyperphagia and higher leptin levels." (PMID 39770898, 2024). "The expression of leptin and resistin is increased in obesity." (PMID 38767687, 2024). "Furthermore, the observed significant reductions with comparatively large effect sizes in PBMC gene expressions of IL-6, IL-1β, and leptin suggest the potential for controlled inflammation in obesity after NS oil supplementation." (PMID 38178093, 2024). "Therefore, in a setting where obesity is likely, keeping leptin levels lower seems to partially control both obesity and T2D." (PMID 39457523, 2024). "However, in the context of obesity and metabolic disorders, the physiological actions of leptin are compromised by the development of leptin resistance." (PMID 39594988, 2024). "However, this concept has been recently challenged by a cross-sectional study of 97 pre-pubertal children with obesity, wherein lower leptin z-scores were identified in patients diagnosed with MASLD through ultrasound." (PMID 39201901, 2024). "In adults, leptin is a predictor of insulin resistance, glucose intolerance, and metabolic syndrome regardless of underlying obesity." (PMID 38254811, 2024). "It was hypothesized that in individuals with obesity, a decrease in serum leptin levels might restore hypothalamic leptin sensitivity and consequently lead to reduced weight gain." (PMID 40302954, 2024). "CUX1-mediated upregulation of RPGRIP1L by binding to FTO intron 1 may reduce leptin sensitivity and lipolysis, promoting the development of obesity." (PMID 39125332, 2024). "The association between obesity and disorders such as depression and anxiety may also be explained by hypothalamic–pituitary–adrenal (HPA) axis disorder, leptin, or microbial mechanisms." (PMID 38654347, 2024). "Obesity may impact blood pressure through various mechanisms, including leptin-mediated increased sympathetic activity and activation of the renin-angiotensin system." (PMID 38462604, 2024). "The results of our study are in agreement with literature data and show that adipokine levels are influenced by the degree of obesity showing significantly higher levels of leptin in the group of female rats given a high-fat diet compared with the levels of this molecule in the control group." (PMID 39683415, 2024). "Children with obesity presented leptin levels higher than those of children with normal BMIs." (PMID 39771030, 2024). "Leptin and visfatin were selected for this study due to their established roles in metabolic and reproductive health, as well as their potential implications in obesity-related complications during pregnancy." (PMID 39683415, 2024). "This leptin-induced aldosterone release is further amplified in obesity due to the reduced anti-aldosterone effects of natriuretic peptides, a consequence of increased neprilysin activity, which results both from mature adipocytes and through kidney release triggered by sympathetic nerve activation." (PMID 39682585, 2024). "Thirdly, in both patients and gerbils, the interplay between adiponectin and leptin levels in serum may significantly influence the development of obesity and diabetes." (PMID 39474247, 2024). "High serum leptin levels in obese individuals, produced by adipose cells, could be a candidate mechanism for explaining the elevated TSH levels in obesity, as it is known that leptin stimulates TSH release." (PMID 38337632, 2024). "For instance, obese individuals appear to exhibit impaired transport of leptin from the bloodstream into the cerebrospinal fluid, a condition observed in diet-induced obesity in minipigs and mice, as well as in mice with selective knockout of leptin receptors in tanycytes." (PMID 39047908, 2024).